RAD50 (RAD50 double strand break repair protein)
Diseases named in the same sentence as RAD50 in open-access papers (continued):
Sharing a sentence is not in itself a finding about the gene and the disease.
esophageal squamous cell carcinoma (3 papers, 2020 to 2021). Esophageal squamous cell carcinoma (ESCC) is a type of esophageal carcinoma (EC) that can affect any part of the esophagus, but is usually located in the upper or middle third. "These rare loss-of-function RAD50 variants were associated with a substantial increased risk of familial esophageal squamous cell carcinoma in high-risk Northern China." (PMID 34572942, 2021). "Unbiased whole-exome sequencing approaches in familial esophageal squamous cell carcinoma (ESCC) initially prioritized RAD50 as a candidate cancer predisposition gene." (PMID 34572942, 2021).
Lynch syndrome (3 papers, 2017 to 2023). An autosomal dominant hereditary neoplastic syndrome characterized by the development of colorectal carcinoma and a high risk of developing endometrial carcinoma, gastric carcinoma, ovarian carcinoma, renal pelvis carcinoma, and small intestinal carcinoma. "For patients without Lynch syndrome, APC was identified as the gene associated with the most mutations (n = 14) and was followed by BRCA1 (n = 8), RAD50 (n = 7), MUTYH (n = 5), ATM (n = 5), and BRCA2 (n = 4)." (PMID 35014770, 2022).
serous ovarian cancer (3 papers, 2013 to 2021). "Here, we sought to investigate the clinical and functional significance of Rad50 in high‐grade serous ovarian cancer (HGSOC)." (PMID 34734468, 2021). "Approximately 50% of high-grade serous ovarian cancers are characterized by HR deficiency, which involves mutations in BRCA1/2, the MRN complex (MRE11, RAD50, NBS1), ATM, RAD51C/D, PALB2, BRIP1, BARD1, and other genes." (PMID 31572446, 2019).
Ad- (2 papers, 2016 to 2021). "In this study, we observed that Ad-RAD50 infection decreased the phosphorylation of cdc25c and cdk1." (PMID 26951044, 2016).
Cockayne syndrome (2 papers, 2016 to 2023). A multisystem condition characterized by short stature, a characteristic facial appearance, premature aging, photosensitivity, progressive neurological dysfunction, and intellectual deficit. "Functionally relevant interactions with TRF2 at low incidence have been reported for other TRF2 interaction partners, including Mre11/Rad50/Nbs1, XPF/ERCC1 and Cockayne syndrome group B protein." (PMID 26799419, 2016).
colorectal mucinous adenocarcinoma (2 papers, 2017 to 2023). An invasive colorectal adenocarcinoma characterized by the presence of extracellular mucin pools that contain malignant glandular epithelial structures. "Importantly, RAD50 was identified as a prognostic biomarker for colorectal mucinous adenocarcinoma (10–15% of all cases) through an integrated analysis of genetic and epigenetic features." (PMID 29189711, 2017).
cystadenocarcinoma (2 papers, 2020 to 2023). A malignant cystic epithelial neoplasm arising from the glandular epithelium. "Literature is reporting that RAD50 high expression associated with aggressive high grade cystadenocarcinomas and low RAD50 linked to better progression free survival." (PMID 37474724, 2023). "High nuclear RAD50 was seen in 90/239 (42.6%) tumours and linked to serous cystadenocarcinoma (p = 0.033), high grade 3 tumours (p = 0.004)." (PMID 35006434, 2020). "High RAD50 expression was associated with aggressive high-grade serous cystadenocarcinomas." (PMID 35006434, 2020).
food allergy (2 papers, 2017 to 2020). Gastrointestinal disturbances, skin eruptions, or shock due to allergic reactions to allergens in food. "We identified two groups of SNPs covering IL5/RAD50 and IL4/KIF3A, which were significantly associated with food allergy." (PMID 29051540, 2017).
HCMV infection (2 papers, 2014 to 2015).
head and neck cancer (2 papers, 2013 to 2018). A primary or metastatic malignant neoplasm affecting the head and neck. "In the current preliminary study we screened the selected regions, where most of already known molecular variants of the RAD50 and MRE11 gene occur, among 358 head and neck cancer patients and 506 controls." (PMID 24079363, 2013). "However, in models where ATM is lost or not functional we observe the opposite effect, as demonstrated by the 32–79% reduction in phosphorylation of RAD50 in the ATM KO FaDu head-and-neck cancer xenograft model treated with AZD6738 for 24 h." (PMID 30385821, 2018).
invasive ductal carcinoma (2 papers, 2017 to 2024). "It is therefore possible that RAD50 R385C may only be associated with invasive ductal carcinoma." (PMID 28241424, 2017). "patient: BRCA2 c.7976G>A het, p.Arg2659Lys and RAD50 c.287T>C het, p.Val96Ala, which are pathogenic and VUS, respectively; the patient has been receiving treatment for Grade 3 triple negative, invasive ductal carcinoma as well, which was diagnosed at the age of 29 years." (PMID 39148954, 2024).
medulloblastoma (2 papers, 2017 to 2022). A malignant, invasive embryonal neoplasm arising from the cerebellum. "Inherited or somatic mutations in the MRE11, RAD50 and NBN genes increase the incidence of tumours, including medulloblastoma (MB)." (PMID 35839783, 2022).
ovarian tumor (2 papers, 2018 to 2021). "Overexpression of Rad50 in A2780 cells significantly promoted ovarian tumour growth, whereas knockdown of Rad50 in SKOV3 cells remarkably reduced tumour burden in mice." (PMID 34734468, 2021). "In this cohort of breast and ovarian tumors, four rare variants in MSH6, one variant in RAD50, one variant in MRE11A, and two variants in RAD51 have been identified." (PMID 30283497, 2018).
Seckel syndrome (2 papers, 2015 to 2021). A rare autosomal recessive inherited syndrome caused by mutations in the ATR gene, RBBP8 gene, CENPJ gene, CEP152 gene, CEP63 gene, NIN gene, DNA2 gene, or TRAIP gene. "Here, we propose that heterozygous variants of WDR62, CEP63, RAD50 and PCNT contribute to additional neurological and extra-neurological abnormalities in affected siblings of the families manifesting MCPH or Seckel syndrome." (PMID 34068194, 2021). "Here, we have provided evidence that heterozygous missense variants of WDR62, CEP63 and RAD50 aggravate the phenotype of MCPH and a PCNT nonsense variant exacerbates the severity of Seckel syndrome features." (PMID 34068194, 2021).
squamous cell carcinoma (2 papers, 2019 to 2021). A carcinoma arising from squamous epithelial cells. "Combination of mutant RAD50 therapy and cisplatin causes dramatic tumor regression in cisplatin-resistant human squamous cell cancer xenografts." (PMID 31767017, 2019). "The potential clinical implication of therapeutically targeting RAD50 in cancers has been demonstrated by dominant negative disruption of RAD50, conferring sensitization to platinum-based chemotherapy in squamous cell carcinoma." (PMID 34572942, 2021).
thyroid cancer (2 papers, 2016 to 2021). "By studying 6 PTMC patients and 6 cancer-free controls, we found that mutations in Rad50 and FANCA reduce DSB repair capacity and may lead to the occurrence of thyroid cancer." (PMID 34215272, 2021). "Interestingly, XRCC5 (Ku80), XRCC6 (Ku70) and RAD50 are members of the non-homologous end joining (NHEJ) DNA repair machinery and are recurrently mutated genes in thyroid cancer according to the Catalogue of Somatic Mutations in Cancer (COSMIC) database." (PMID 26870890, 2016).
acute leukemia (1 paper, 2013). A clonal (malignant) hematopoietic disorder with an acute onset, affecting the bone marrow and the peripheral blood. "In childhood acute leukemia we cannot exclude the copy number variations of the RAD50 gene as mechanism for increasing risk." (PMID 24093751, 2013). "With this in mind, we decided to simultaneously analyze the alterations in MRE11, RAD50 and NBN genes in Polish children with acute leukemia." (PMID 24093751, 2013).
acute lymphoblastic leukemia (1 paper, 2013). Leukemia with an acute onset, characterized by the presence of lymphoblasts in the bone marrow and the peripheral blood. "In our another study we confirmed the association of the variant allele of the RAD50 rs171660505 with decreased risk of the childhood acute lymphoblastic leukemia." (PMID 24079363, 2013).
Arthritis (1 paper, 2014). Inflammation of a joint. "The affected 5q LOH interval harbors several cytokine genes (including IL-3, IL-4, IL-5, IL-13, and CSF2), a gene associated with arthritis susceptibility (SLC22A4), a DNA repair gene (RAD50), and a gene that promotes Type 1 interferon responses (IRF1)." (PMID 25107306, 2014).
astrocytoma (1 paper, 2018). "Besides, CREB expression and activation is directly related with the astrocytoma grade and participates in the up-regulation of genes involved in DNA repair such as RAD50 as well as genes promoting cell proliferation and cytokinesis in PC12 cells." (PMID 29543748, 2018).
Ataxia (1 paper, 2023). Ataxia refers to impaired coordination of voluntary muscle movement. "We successfully generated multiple tumors and typical A-T phenotypes with corresponding histological abnormalities, telangiectasia, immunological abnormalities, and ataxia in rad50 mutant medaka using the CRISPR/Cas9 system." (PMID 37098078, 2023).
B-cell neoplasm (1 paper, 2021). A group of heterogeneous lymphoid tumors generally expressing one or more B-cell antigens or representing malignant transformations of B-lymphocytes. "Out of 15 patients, 4 (26.6%) with subsequent mature B-cell neoplasms had germline pathogenic mutations in cancer susceptibility genes; MUTYH and WRN in 2 subsequent DLBCL patients and RAD50 and LZTR1 in 2 subsequent PCM patients." (PMID 34093829, 2021).
brain tumour (1 paper, 2014). "More importantly, in both the brain tumour cells, KNS60 and ONS76, we observed a consistent decrease in the expression of gene coding for ATM and RAD50 proteins, which are involved in HR pathways." (PMID 25307264, 2014).
childhood leukemia (1 paper, 2013). An acute or chronic leukemia that occurs during childhood. "In the current study we screened the selected regions, of the MRE11, RAD50 and NBN gene, where most of already known molecular variants occur, among 220 childhood leukemia samples and controls." (PMID 24093751, 2013).
chondrosarcoma (1 paper, 2023). A malignant cartilaginous matrix-producing mesenchymal neoplasm arising from the bone and soft tissue. "Olaparib decreased cell survival of CH2879 chondrosarcoma cells and the radiosensitivity was associated with mutations in homologous recombination repair genes, such as RAD50, SMARCA2, and NBN." (PMID 36768638, 2023).
chromosome instability syndromes (1 paper, 2023). "Traditionally, the MRE11/RAD50/NBN deficiency causes chromosome instability syndromes in humans." (PMID 37024481, 2023). "Thus, our findings suggest that Nbn or Rad50 deficiency zebrafish may afford an opportunity to understand the mechanism of chromosome instability syndromes in humans." (PMID 37024481, 2023).
Cirrhosis (1 paper, 2013). A chronic disorder of the liver in which liver tissue becomes scarred and is partially replaced by regenerative nodules and fibrotic tissue resulting in loss of liver function. "When compared with non-cirrhotic liver, HBV-associated cirrhosis displayed a dramatic repression of all shelterin and non-shelterin factors except HMRE11A and RAD50." (PMID 24020493, 2013).
Crohn disease (1 paper, 2013). A gastrointestinal disorder characterized by chronic inflammation involving all layers of the intestinal wall, noncaseating granulomas affecting the intestinal wall and regional lymph nodes, and transmural fibrosis. "An association of the G allele of the RAD50 SNP with Crohn's disease (CD) susceptibility has also been reported." (PMID 24093751, 2013).
falciparum malaria (1 paper, 2012). "A study done in a Thai population revealed that the SNP rs1881457, which is located in the same haplotype block in 5q31-33 region with the RAD50 gene and the promoter of IL13 is significantly associated with severe falciparum malaria." (PMID 22905743, 2012).
head and neck squamous cell carcinoma (1 paper, 2020). A squamous cell carcinoma that arises from any of the following anatomic sites: lip and oral cavity, nasal cavity, paranasal sinuses, pharynx, larynx, and salivary glands. "Increased toxicity was associated with DSB accumulation as evidenced In a head and neck squamous cell carcinoma model, RAD50 blockade resulted in cisplatin chemosensitization." (PMID 35006434, 2020).
hyperandrogenism (1 paper, 2024). Excessive secretion of androgens from the adrenal glands or gonads. "Similarly, SNPs within YAP1, TOX3 and IRF1/RAD50 were only significant in the lean group, and have previous association with ovulatory dysfunction, hyperandrogenism and increased testosterone levels respectively." (PMID 38408933, 2024).
laryngeal carcinoma (1 paper, 2013). Carcinoma that arises from the laryngeal epithelium. "To our knowledge the first prospective investigation of its kind, we have shown that MRE11 and RAD50 genes do not contribute to laryngeal cancer." (PMID 24079363, 2013).
Li-Fraumeni syndrome (1 paper, 2021).
lung adenocarcinoma (1 paper, 2025). A carcinoma that arises from the lung and is characterized by the presence of malignant glandular epithelial cells. "Germline variants in RAD50 have been reported in patients with lung adenocarcinoma, but they have not been linked to an increased risk of LUAD." (PMID 40430005, 2025).
lung squamous cell carcinomas (1 paper, 2015). "Missense point mutations in an extended analysis of ATM, MRE11A, RAD50 and NBN are present in 16/212 lung squamous cell carcinomas (7 %) are present in the TCGA database." (PMID 26438152, 2015).
malaria (1 paper, 2009). Malaria is a serious and sometimes fatal disease caused by a parasite that commonly infects a certain type of mosquito which feeds on humans. "In this study rs1881457 was found to be significantly associated with severe malaria, and this SNP was included in a haplotype block encompassing the whole RAD50 gene and the promoter of IL13." (PMID 19840389, 2009). "A haplotype block spanning 97 kb encompassing RAD50 gene and IL13 promoter region that was associated with severity of malaria was identified in a Thai population." (PMID 19840389, 2009).
MALT lymphoma (1 paper, 2009). An indolent, extranodal type of non-Hodgkin lymphoma composed of small B-lymphocytes (centrocyte-like cells). "Our observation of possible associations of SNPs in RAD50 with DLBCL and MZ/MALT lymphomas may contribute to the refinement of biological hypotheses for confirmation in larger association studies and functional studies." (PMID 19917125, 2009).
meningioma (1 paper, 2022). A generally slow growing tumor attached to the dura mater. "One NF2 wild type meningioma (28M) had PDGFRB and RAD50 mutations." (PMID 35049691, 2022). "Since in vitro studies demonstrated that mutant RAD50 may sensitize tumor cells to radiation, we may speculate that RAD50 mutant meningiomas may be more sensitive to radiotherapy." (PMID 35049691, 2022).
metastatic melanoma (1 paper, 2021). A melanoma that has spread from its primary site to another anatomic site. "Higher ILF2/U2AF2 expression and a consequently significantly higher expression of RAD50 were observed in metastatic melanoma tissues compared to primary tissues." (PMID 34709752, 2021). "Moreover, RAD50 knockdown blocked the enhanced cell proliferation induced by ILF2‐OV in metastatic melanoma." (PMID 34709752, 2021). "Then, RAD50 knockdown was evaluated to determine whether RAD50 plays a role in metastatic melanoma cell proliferation." (PMID 34709752, 2021). "Our results demonstrated the regulatory role of ILF2 controlling the expression of RAD50 and ATM pathway activation, which consequently enhanced the efficiency of DDR by activating HR in metastatic melanoma cells." (PMID 34709752, 2021). "Our results show that ILF2 and U2AF2 may have implications in RAD50 and ATM mRNA processing in metastatic melanoma." (PMID 34709752, 2021). "In conclusion, RAD50 plays a significant role as a downstream effector of ILF2, and it may have implications in controlling DDR in metastatic melanoma cells." (PMID 34709752, 2021). "Also, our evidence from RPPA and in vitro assays indicated RAD50 and ATM proteins as downstream effectors of the ILF2‐U2AF2 complex in metastatic melanoma cells." (PMID 34709752, 2021). "Consequently, RAD50 and ATM improve DDR and promote resistance to TMZ in metastatic melanoma." (PMID 34709752, 2021).
metastatic tumors (1 paper, 2021). "The metastatic tumors retained most of the genetic variants found in the original tumors, but some cases had additional CNVs, including copy number gains for the KRAS, AKT3, RICTOR, FGFR, and FANCD2 genes, and copy number losses for the MYC and RAD50 genes." (PMID 34422662, 2021).
non-small cell lung carcinoma (1 paper, 2019). A group of at least three distinct histological types of lung cancer, including non-small cell squamous cell carcinoma, adenocarcinoma, and large cell carcinoma. "In non-small cell lung cancer, upregulation of RAD50 may be used to predict shorter RFS." (PMID 31767017, 2019).
parasite infection (1 paper, 2024). "In contrast to DNA-PK, no alterations were found in the phospho-Rad50 protein levels by immunoblotting during the parasite infection." (PMID 38433244, 2024).
pediatric asthma (1 paper, 2011). "Our GWAS dataset supported an association between identical SNPs reported in ORMDL3/GSDMB/GSDMA, IL5/RAD50/IL13, HLA-DR/DQ, and SMAD3 and pediatric asthma (P<0.05)." (PMID 21814517, 2011).